UBE2C (ubiquitin conjugating enzyme E2 C)
Diseases named in the same sentence as UBE2C in open-access papers (continued):
Sharing a sentence is not in itself a finding about the gene and the disease.
cancer (continued). "Here, our data showed that knockdown of UBE2C significantly attenuated cell proliferation, migration, and invasion in HCC cells in vitro, further supporting that UBE2C functions as a bona fide oncogene in human cancers." (PMID 30914455, 2019). "It is worthy to note that TSPYL2 showed down-regulation in most of the 27 cancers and also very weak to strong negative correlation with UBE2C in most of these studied cancers." (PMID 31067633, 2019). "Overexpression of UBE2C activated ERK signal pathway and promoted cancer cell proliferation." (PMID 30116193, 2018). "The results revealed that UBE2C silencing down-regulated the phosphorylation of the ERK1/2 in BGC-823 cancer cells, while UBE2C overexpression up-regulated phosphorylation of the ERK1/2 in SGC-7901 cancer cells." (PMID 30116193, 2018). "Using IHC, we found UBE2C to be overexpressed in 28/32 cancers, 2/11 CIN3/CIS and none of the CIN1 or 2 (Fisher's exact test p = 2.2 e-11)." (PMID 21338529, 2011). "The analysis of immunohistochemical data revealed that UBE2C and AURKA expression levels are higher in undifferentiated tumors of cervical (p < 0.0001 and p < 0.004, for UBE2C and AURKA respectively) and breast (p < 0.001 and p < 0.0001, for UBE2C and AURKA respectively) cancer samples." (PMID 20630075, 2010). "Additionally, three cancer cell subpopulations with distinct chemosensitivity profiles were identified; Subpopulation 2, characterized by high expression of CCNA2, UBE2C, and CENPF, demonstrated significantly reduced sensitivity to methotrexate, doxorubicin, cisplatin, ifosfamide, and etoposide." (PMID 42099775, 2026). "Moreover, genes that are upregulated and downregulated at both RNA and protein levels across multiple types of cancers were identified and defined as PCUGs and PCDGs, respectively, which encompass a large number of oncogenes such as MKI67, TRIP13, SMC4, UBE2C, CDK1, and TOP2A." (PMID 39884577, 2025). "Furthermore, UBE2C exhibited significant positive or negative correlations with the infiltration of 12 other immune cells in the majority of the cancers." (PMID 38370368, 2024). "However, the mechanism of action of UBE2C in LUAD and its implications in diagnosis, targeted therapy of LUAD and immunotherapy, and even in pan-cancer, remain unclear." (PMID 38370368, 2024). "However, the possible regulatory mechanisms of several important but undruggable cell-cycle-related proteins, such as ubiquitin-conjugating enzyme E2 C (UBE2C), in pan-cancer are still unknown." (PMID 37958642, 2023). "Interestingly, the targeting of PI3K/mTOR signaling pathway by dactolisib decreased the UBE2C levels in all cancer cell lines, regardless of their different levels of PI3K activation." (PMID 37215954, 2023). "This suggests that UBE2C and PLK1 may play important roles in the development of pan-cancer." (PMID 37958642, 2023). "UBE2C + cancer cells (Epi-C6) were mainly enriched in the following gene sets: MYC target V1, cell cycle, AKT and TGF-β signaling pathways and other gene sets; thus, these cells may promote the progression of cancer through these pathways." (PMID 36434043, 2022). "As far as we know, there is currently no pan-cancer analysis of UBE2C." (PMID 35571064, 2022). "For the cancer cell subtypes, we found that compared with Clara-like cancer cells (Epi-C1) and CRABP2 + cancer cells (Epi-C3), the proportions of both TM4SF1 + (Epi-C0) and UBE2C + (Epi-C6) cancer cells were constantly increased during the invasive process of LUAD and dramatically elevated in IAC." (PMID 36434043, 2022). "Moreover, gene interaction networks revealed several key genes and cancer-related pathways that may role for early NSCLC transformation and disease progression, including FAM83A, ZNF696, UBE2C, RECK, TIMM50, GEMIN7, and XPO5." (PMID 35309509, 2022). "First, UBE2C has not been identified as an effective biomarker in a variety of cancer samples." (PMID 34950739, 2021).
cancer (continued). "However, a systematic analysis of the molecular characterization and functional effects of UBE2C on 33 cancer types is still lacking." (PMID 34950739, 2021). "As TSPYL2 was under-expressed in most cancers and showed negative correlations with UBE2C that were very weak to moderate, we analyzed the RNA–RNA association between TSPYL and UBE2C using RNAup webserver and also RNA–protein interactions using RPISeq." (PMID 31067633, 2019). "The mechanisms governing the dysregulation of UBE2C in cancer is not defined very well so far." (PMID 29904125, 2018). "UBE2C may be a marker for diagnosis of nonpalpable breast lesions but not benign or malignant tumors in mammography core biopsies." (PMID 24699941, 2014). "Depletion of UBE2C in cancer cells by UBE2C-siRNA redistributes the cell cycle phases, while bortezomib or cell-cycle inhibitor-779 (CCI-779) stabilizes mitotic cyclins and prevents cell cycle progression via attenuation of UBE2C transcription and mRNA stability." (PMID 23587173, 2013). "We found that there was a significant positive correlation between UBE2C and TMB in 33 cancers except ESCA, KIRP, COAD and THYM, and there was a negative correlation between UBE2C and TMB in ESCA, KIRP, COAD and THYM." (PMID 38370368, 2024). "Then, immune checkpoints analysis shown that UBE2C had a negative correlation with immune checkpoints, such as CD274(PD-1), PDCD1(PD-L1), CTLA4, TIGIT, LAG3, HAVCR2, and PDCD1LG2 in a great many cancers." (PMID 38370368, 2024). "In agreement with the previous studies, our data found significant DNA hypomethylation of UBE2C in CHOL, KIRC, and PCPG tumor tissues and a negative correlation between the methylation levels of UBE2C and its expression levels in multiple cancer types." (PMID 35804892, 2022). "Compared with MDA-MB-231 cells, MCF-7 cells expressed lower levels of UBE2C protein and mRNA; this result was supported in NCI-60 human cancer cells database (data not shown)." (PMID 24699941, 2014). "Our research revealed a positive correlation between UBE2C expression and immune scores within the TME matrix across four cancer types (THCA, LUAD, LIHC, and LGG), while a negative correlation was observed in the case of seven cancer types (UCS, TGCT, READ, LUSC, LAML, and COAD)." (PMID 38370368, 2024). "Seven up-regulated genes including CYC1, MIF, LAMB3, TUBB2, UBE2C and TRAP1 had been previously proposed as candidate common cancer biomarkers based on a previous extensive comparison among various cancers and normal tissues which did not, however, include NPC or NP." (PMID 18570662, 2008). "However, to the best of our knowledge, no targeted agents against UBE2T, UBE2C, BIRC5, or USP9X, either approved or in development, can be found in The Drug Gene Interaction Database or Genomics of Drug Sensitivity in Cancer database, while the only USP7 inhibitor, P22077, has not been tested in BC." (PMID 33671201, 2021).
tumor (202 papers, 2004 to 2026). "Increased UBE2C expression is associated with larger tumor size, higher grade, lymphovascular invasion, LN metastasis, and poor survival in various tumors." (PMID 39543244, 2025). "To comprehend the mutated genes within the tumours, we conducted an analysis of the mutations present in cells belonging to both the high UBE2C+ tumour cell score group and the low UBE2C+ tumour cell score group." (PMID 38894657, 2024). "Taken together, higher UBE2C gene expression appeared to be a useful prognostic indicator associated with poor prognosis and higher frequencies of tumor metastasis and progression." (PMID 38577722, 2024). "In order to delve deeper into the gene regulatory network associated with C2 UBE2C+ tumour cells, we employed pySCENIC to assess the specific regulation of diverse tumour cell populations." (PMID 38894657, 2024). "The results revealed that surgical margin, primary tumor staging, histological variants, and UBE2C expression were significantly correlated with local recurrence-free survival and metastasis-free survival." (PMID 38102624, 2023). "At the same time, compared with the diagnostic efficiency of tumor markers alone, UBE2C combined with clinical markers has higher diagnostic efficiency, which reduces the misdiagnosis and missed diagnosis rate of patients to a certain extent." (PMID 35568702, 2022). "We found that UBE2C was upregulated in tumour tissues and was associated with poor overall survival in HNSCC." (PMID 35615976, 2022). "Grouped by gender (P < 0.001), tumor grade (P < 0.001), and race (P < 0.001), high expression of UBE2C was linked to shorter overall survival." (PMID 36385010, 2022). "Correlation analysis between UBE2C expression and clinical factors showed that UBE2C expression was associated with tumor metastasis, and the positive rate of metastasis was high in patients with high expression." (PMID 35568702, 2022). "When we stratified the protein expression based on BC histological subtypes, high UBE2C protein expression was strongly associated with ductal NST BC tumour compared to other types (p < 0.001)." (PMID 35124721, 2022). "Although the protein encoded by UBE2C will decrease cyclins, its overexpression leads to chromosome missegregation and tumor formation." (PMID 34204115, 2021). "In the present study, we clarified that expression of FANCB, KIF15, KIF4A, ERCC6L, and UBE2C are regulated by DNA methylation changes of their promoter CpGis and closely associated with tumor prognosis in HCC using the TCGA database." (PMID 32703154, 2020). "Univariate analysis of DFS, DMFS, and OS indicated that positive LN involvement, large tumor size, high histologic grade, and high UBE2C expression were significantly associated with poor survival in all patients (P < 0.05)." (PMID 32039034, 2019). "To identify potential associations between UBE2C mRNA expression and clinicopathological parameters, we compared its abundance amongst diverse subgroups based on tumor grade." (PMID 30914455, 2019). "For training cases, univariate analysis showed that the factors of T stage, lymph nodes status, TNM stage, tumor grade, UBE2C expression and MGP expression were significantly associated with disease-free survival (DFS) (P<0.05)." (PMID 27556859, 2016). "The Cox regression analysis showed that T stage, lymph nodes status, TNM stage, tumor grade, vascular invasion, UBE2C expression and MGP expression were significantly associated with overall survival (OS) (p<0.05)." (PMID 27556859, 2016). "In summary, UBE2C appears to be a tumor‐specific, high‐expression risk gene, and targeting UBE2C may offer therapeutic benefits and improve patient survival." (PMID 40135850, 2025). "However, rapamycin, an autophagy activator, reversed the tumor growth and apoptosis inhibition caused by UBE2C overexpression." (PMID 39403142, 2024).
tumor (continued). "Recently, an increasing number of studies demonstrated that UBE2C was highly expressed in various human malignancies, in which the high expression of UBE2C could be closely associated with tumor stage and clinical prognosis." (PMID 38637730, 2024). "Finally, we assessed the correlation between immune checkpoint‐associated genes, UBE2C+ tumour cells score composition genes, OS and risk scores, as well as immune checkpoint‐associated gene expression level differences between the two groups." (PMID 38894657, 2024). "Notably, the C2 UBE2C+ tumour cells demonstrated a close association with cell mitosis and the cell cycle, exhibiting robust proliferative capabilities." (PMID 38894657, 2024). "Hence, the abnormal expression of UBE2C will cause the hyperactivity of the APC/C-dependent ubiquitination in tumor cells, which accelerates the cell cycle and eventually leads to malignant transformation." (PMID 37535572, 2023). "Of note, UBE2C, which may be a good indicator of tumor proliferation, is positively associated with reductions in overall survival and highly associated with tumor grade." (PMID 35812372, 2022). "We also observed that the UBE2C gene expression was associated with increasing histological grades, indicating that it may be a potential novel target for tumor progression prediction." (PMID 35812372, 2022). "In addition, UBE2C expression was markedly associated with tumor mutation burden (TMB), microsatellite instability (MSI), immune cell infiltration, and diverse drug sensitivities." (PMID 34858987, 2021). "In addition, we found that UBE2C expression was markedly associated with tumor mutational burden (TMB), microsatellite instability (MSI), immune cell infiltration, and diverse drug sensitivities." (PMID 34858987, 2021). "High UBE2C expression has also been was associated a highly malignant tumor phenotype." (PMID 34488675, 2021). "Moreover, a higher expression of the CDCA3 and UBE2C genes was significantly associated with higher tumor histologic grades." (PMID 34577856, 2021). "Moreover, higher UBE2C expression was also associated with advanced tumor grade of HCC and predicted worse clinical outcomes for HCC patients." (PMID 30914455, 2019). "Additionally, UBE2C has been associated with decreased overall length of survival and increased tumor aggressiveness in GBM." (PMID 31475119, 2019). "Indeed, UBE2C expression is commonly observed to be upregulated in the realm of malignancies and hematologic disorders, displaying a direct association with heightened tumour proliferation and aggressiveness." (PMID 38894657, 2024). "Treating tumor cell lines with the metabolically active enantiomer L-lactate for 15 min to identify previously unrecognized functions for the metabolite, the team found one of the most affected proteins to be UBE2C, a cell cycle-associated ubiquitin-conjugating enzyme." (PMID 37587111, 2023). "Higher expressions of CDCA3 and UBE2C were significantly associated with higher histologic grades, but not with other clinical features, including age, clinical stage, lymphatic invasion, venous invasion, primary therapy outcome, personal tumor status, and vital status." (PMID 34577856, 2021). "In conclusion, SIX5 functions as a critical oncogenic driver in GBM, regulated by KDM5C and promoting tumor progression through UBE2C-mediated activation of AKT/mTOR signaling and glycolytic reprogramming." (PMID 41939887, 2026). "Among the E2s, a significant role in tumour progression and resistance to many pharmacological treatments is played by UBE2C (also known as UbcH10)." (PMID 41492994, 2026). "The IHC results of Ki67 and TOP2A demonstrated that combination of UBE2C knockdown and doxorubicin treatment had the strongest anti‐tumor effect." (PMID 40729680, 2025). "A heatmap of the 11 mRNA expression levels of the tumor samples displayed that the seven genes, including CCNB1, CCNB2, CHEK1, FEN1, PTTG1, RACGAP1, and UBE2C, had higher expression levels in the tumor tissue." (PMID 41009526, 2025).
tumor (continued). "These pathways are crucial for tumor cell proliferation, genomic stability, and metabolic reprogramming, further underscoring the central role of UBE2C in the development of HCC." (PMID 40290433, 2025). "Our examinations showed a significant overexpression of five genes (CCNB1, CCNB2, PTTG1, RACGAP1, and UBE2C) in the tumor samples." (PMID 41009526, 2025). "In the Asian population, upregulated genes such as AKR1B10, UBE2C, and S100P are involved in immune modulation and tumor progression." (PMID 41216224, 2025). "It is notable that we have identified a distinct cell population within tumours, characterized by a notable upregulation of UBE2C." (PMID 38894657, 2024). "Both cells play unique roles in cell differentiation and cell cycle and are closely related to C2 UBE2C+ tumour cells." (PMID 38894657, 2024). "We found that a positive correlation between UBE2C expression and tumor grade, as well as stage in LUAD patients." (PMID 38370368, 2024). "The findings revealed a robust interaction between UBE2C+ tumour cells and PARs, the regulatory receptors governing the activity of the cell cycle regulatory kinase ERK1/2,34, 35 thus providing further substantiation for our observations." (PMID 38894657, 2024). "Cell cycle analysis and enrichment analysis showed that C2 UBE2C+ tumour cells had high proliferation and was mainly enriched in DNA synthesis and replication and mitotic pathway." (PMID 38894657, 2024). "MYC, EZH2 and CTNNB1 were the primary stemness genes with high expression levels in C2 UBE2C+ tumour cells." (PMID 38894657, 2024). "As a result, genes encoding ubiquitin conjugating enzymes or ligases, such as UBE2T, UBE2C, and CBLC, were up‐regulated in tumor tissues, while genes encoding deubiquitinating enzymes like OTUD1 and USP12 were down‐regulated." (PMID 37983609, 2024). "The PDX models showed that treatment with sh-UBE2C resulted in significant reductions in tumor volume compared with tumor volumes in the control group, indicating that silencing UBE2C had a therapeutic effect on the progression of BCa." (PMID 38949026, 2024). "Considering the in vitro results, the effect of UBE2C silencing in the tumor formation of AML cells was explored in tyhe nude mice." (PMID 38637730, 2024). "The differential expression of UBE2C in different tumor types suggested that UBE2C has various regulatory mechanisms in different tumor types." (PMID 38577722, 2024). "In 2019, a study illustrated a significant decrease in the expression of UBE2C, which acts to regulate tumor cell proliferation and increase tumor invasiveness, after high expression of miR-381-3p was observed in LNCaP and PC-3 cells." (PMID 38818039, 2024). "This study provides valuable insights and directions for future research on UBE2C -based anti-tumor therapy research." (PMID 38370368, 2024). "Several of the uniquely upregulated genes are previously shown to be involved in tumor cell proliferation such as UBE2C, GABRP, and FOXC1." (PMID 39198859, 2024). "Recently, the prognostic significance, and immunological functions of ubiquitin‐conjugating enzyme 2C (UBE2C) has been studied across various tumor types." (PMID 38577722, 2024). "Patients in the TCGA cohort were categorized into two groups according to the median UBE2C+ tumour cell score: the high UBE2C+ tumour cell score group and the low UBE2C+ tumour cell score group." (PMID 38894657, 2024). "Meanwhile, knockdown of the transcription factor CREB3, which is highly active in UBE2C+ tumour cells, significantly impedes the proliferation, migration and invasion of GC cells." (PMID 38894657, 2024). "Our study highlights the potential of UBE2C as a predictive marker for immunotherapy efficacy and underscores its significance as a potential target for tumor immunotherapy." (PMID 38370368, 2024). "Conversely, AKT inhibitor VIII, an AKT inhibitor that responds well in GC, displayed enhanced sensitivity in the cohort characterized by a low UBE2C+ tumour cell score." (PMID 38894657, 2024).